SLC44A2 (solute carrier family 44 member 2 (CTL2 blood group))
Diseases named in the same sentence as SLC44A2 in open-access papers (continued):
Sharing a sentence is not in itself a finding about the gene and the disease.
venous thromboembolism (1 paper, 2023). Occlusion of the lumen of a vein by a thrombus that has migrated from a distal site via the blood stream. "More recently, venous thromboembolism recurrence in Thai patients was shown to be linked to SLC44A2 p.Arg152Gln variant." (PMID 36695047, 2023). "In humans, SLC44A2 has been identified as a susceptibility locus for venous thromboembolism (VTE), which generated heightened interest in its function and attention has shifted to its role in thrombosis." (PMID 36695047, 2023). "Indeed, SLC44A2 polymorphisms have been identified in genome‐wide association studies to have an allele‐specific association with venous thromboembolism and cardiovascular diseases." (PMID 36695047, 2023).
infection (12 papers, 2014 to 2025). The state of being infected such as from the introduction of a foreign agent such as serum, vaccine, antigenic substance or organism. "The elevated serum TGF-β concentration and p-SMAD2 were further confirmed in Ang II–infused Apoe–/– mice by Lenti-Slc44A2 infection." (PMID 38916960, 2024). "It remains to be determined whether the rs2288904-A SNP in SLC44A2 that is protective against VTE might also (negatively) influence the host response to infection, or certain routes of infection that are more reliant upon platelet immune cell function." (PMID 32314961, 2020).
cancer (4 papers, 2015 to 2025). A tumor composed of atypical neoplastic, often pleomorphic cells that invade other tissues. "However, two groups have implicated choline transport by SLC44A2/CTL2 in human cancer cells." (PMID 26463873, 2015). "Nonetheless, the expression patterns of SLC44A2, as well as its impact on mitochondrial metabolism and malignancy progression in human cancers, including CRC, remain largely unexplored." (PMID 40592838, 2025). "To further elucidate the role of SLC44A2 in different human cancer types, we conducted a pan-cancer analysis using Sangerbox 3.0." (PMID 40592838, 2025). "Notably, deletion of SLC44A2 impairs adhesion but increases proliferation in cultured mesenchymal lung cells, suggesting its potential involvement in cancer cell proliferation and invasion." (PMID 40592838, 2025). "However, the effects of SLC44A2 on malignant phenotypes and mitochondrial metabolism in human cancers remain unexplored." (PMID 40592838, 2025). "However, the effects of SLC44A2 on mitochondrial metabolism and malignant progression in human cancers remain largely unexplored." (PMID 40592838, 2025). "Notably, deletion of SLC44A2 impairs adhesion but increases proliferation in cultured mesenchymal lung cells, implying that SLC44A2 may play a role in the malignant phenotypes of human cancers." (PMID 40592838, 2025). "Untargeted metabolome analysis revealed that that SLC44A2-regulated metabolites were primarily enriched in energy metabolism pathways, including the “TCA cycle,” “oxidative phosphorylation,” and “central carbon metabolism in cancer”." (PMID 40592838, 2025). "However, the influence of SLC44A2 on the aggressive characteristics of human cancers has not previously been studied." (PMID 40592838, 2025).
tumor (3 papers, 2014 to 2025). "Our findings indicated that forced expression of CPT2 significantly rescued the suppression of cell proliferation and invasion in vitro, as well as tumor growth and metastasis in vivo, which were caused by SLC44A2 overexpression." (PMID 40592838, 2025). "The results indicated that both mRNA and protein levels of SLC44A2 were significantly downregulated in CRC tumor tissues compared to normal tissues." (PMID 40592838, 2025). "Detection of SLC44A2 expression by qRT-PCR analysis in 35 pairs of human CRC tissues and adjacent non-tumor tissues also confirmed the down-regulation of SLC44A2 in CRC." (PMID 40592838, 2025). "Immunohistochemical (IHC) staining confirmed significant SLC44A2 upregulation in tumors from the SLC44A2-overexpressing group compared to the control group, indicating that SLC44A2 overexpression inhibited tumor growth." (PMID 40592838, 2025). "Collectively, these findings indicate that SLC44A2 acts as a crucial tumor suppressor in CRC progression." (PMID 40592838, 2025). "In summary, our study provides a molecular basis for SLC44A2 as a potential tumor suppressor in CRC by downregulating CPT2-mediated mitochondrial FAO in a MUL1-dependent manner (Graphical abstract, generated using the Microsoft PowerPoint software)." (PMID 40592838, 2025). "Stable overexpression of SLC44A2 in HCT116 cells led to a significant decrease in xenograft tumor growth and weights compared to the control group." (PMID 40592838, 2025). "We also examined the association between CPT2 and SLC44A2 in tumor tissues from CRC patients using IHC staining-based histological analysis and found a notable inverse correlation between CPT2 and SLC44A2 protein levels." (PMID 40592838, 2025). "Together, SLC44A2 functions as a critical tumor suppressor in CRC and potential therapeutic target in the treatment of this malignancy." (PMID 40592838, 2025). "Consistent with this, IHC staining of CPT2 in tumor tissues from nude mice showed significantly lower CPT2 levels in the SLC44A2 overexpression group compared to the control group." (PMID 40592838, 2025). "Additionally, we used the online TIMER (Tumor IMmune Estimation Resource) database to examine the relationship between SLC44A2 expression and tumor-infiltrating immune cells in CRC." (PMID 40592838, 2025). "In this study, we demonstrate that SLC44A2 inhibited the short- and long-term proliferation of CRC cells, as evidenced by both in vitro MTS cell viability, Edu and colony formation assays, and in vivo xenograft tumor growth assay in nude mice." (PMID 40592838, 2025). "SL exposure also induced changes in the expression of genes involved in metabolic functions in tumor and stem cells (ALDH1B1, ABCB1, SLC3A2, SLC44A2, SLC31A2, SLC7A11, CYP24A1, PTGS2/COX2, PPRC1), cytokines (CCL3L3, GDF15) and growth and differentiation factors (PGF, TGFBR11 and FOXD1)." (PMID 24742967, 2014). "Our results indicate that SLC44A2 acts as a tumor suppressor in CRC by downregulating CPT2-mediated mitochondrial fatty acid oxidation via increasing the interaction between MUL1 and CPT2, supporting SLC44A2 as a potential therapeutic target in the treatment of this malignancy." (PMID 40592838, 2025).
cardiovascular disease (2 papers, 2023 to 2024). "However, the precise role of SLC44A2 in cardiovascular disease is not well understood." (PMID 38916960, 2024). "SLC44A2, a member of the solute carrier series 44 (SLC44) family, remains undercharacterized in the context of cardiovascular diseases." (PMID 38916960, 2024).
hematological disorder (1 paper, 2023). "In summary, our data demonstrate that defective alleles of SLC44A2 occur in humans, do not preclude viability, and are not necessarily associated with hematological disorders observed in murine models." (PMID 36695047, 2023). "Unexpectedly, the absence of SLC44A2 from platelets and RBCs does not cause any apparent hematological disorder." (PMID 36695047, 2023).
vascular disorder (1 paper, 2019). A general term used to describe any disease affecting blood vessels]. "Among the identified genes in this study, several genes including MTHFR, NOS3, SLC44A2, and NOTCH2 are associated with prothrombotic risk factors and various vascular disorders." (PMID 32038468, 2019).
SLC44A2 also shares sentences with these, for which no sentence is quoted: breast carcinoma (2 papers); Ménière disease (2); adrenocortical carcinoma (1); autoimmune disease (1); bladder urothelial carcinoma (1); cervical squamous cell carcinoma (1); cholangiocarcinoma (1); chronic thromboembolic pulmonary hypertension (1); coronary artery disease (1); endocervical adenocarcinoma (1); esophageal adenocarcinoma (1); esophageal carcinoma (1); gastric adenocarcinoma (1); glioblastoma multiforme (1); Hearing impairment (1); helminth infection (1); idiopathic pulmonary arterial hypertension (1); invasive breast carcinoma (1); lung adenocarcinoma (1); lung carcinoma (1); lung injury (1); lung squamous cell carcinoma (1); malnutrition (1); Pan (1); pheochromocytoma and paraganglioma (1); prostate adenocarcinoma (1); renal clear cell carcinoma (1); renal papillary cell carcinoma (1); sensorineural hearing loss (1); skin cutaneous melanoma (1).
A further 4 diseases each share a sentence with SLC44A2 in 1 paper.